CCL3 (C-C motif chemokine ligand 3)
Diseases named in the same sentence as CCL3 in open-access papers (continued):
Sharing a sentence is not in itself a finding about the gene and the disease.
tumor (continued). "Chemokines such as CCL3 play a crucial role in this process by guiding the migration of NK cells toward the tumor environment." (PMID 40551137, 2025). "Previous studies have emphasized the critical role of CCL3 in facilitating NK cell migration to tumor sites." (PMID 40551137, 2025). "They identified loss of Plaur, Mif and Serpine 1 to be responsible for a growth disadvantage of murine ID8 OvCa cells in vivo, whereas Ccl3, Calr and Ccl7 knockout (KO) tumor cells were substantially enriched and formed distinct lesions within the tumors." (PMID 39837825, 2025). "CCL3 enhances the chemotactic response of NK cells, facilitating their accumulation in and penetration of tumor tissues where they can exert their cytotoxic effects more efficiently." (PMID 40551137, 2025). "Downregulated were the critical genes CAV1, VWF, and DCN, suggesting loss of tumour-suppressive functions, and upregulated were SCGB2A1, CLDN4, and immune-related genes CCL3 and GZMB, promoting tumour growth and immune evasion." (PMID 41312167, 2025). "This study positions CCL3 as a key regulator of T-cell functionality in the tumor microenvironment and a potential target for boosting immunotherapeutic efficacy." (PMID 41153795, 2025). "As already elaborated, tumor-cell-derived CCL3 activates the MAPK pathway, leading to the production of IL-1β, IL-6 and TNF-α." (PMID 41153795, 2025). "By quantitative PCR (qPCR), we confirmed that Il1a, Ccl2, and Ccl3 mRNAs were virtually undetected in the tumor cells but were expressed predominantly in the CD45+ hematopoietic cells and, to a lesser degree, in the VE-cadherin+GFP– endothelial cells." (PMID 40131370, 2025). "These cells release tumor necrosis factor (TNF)-α and CC motif chemokine ligand 3 (CCL3, formerly known as macrophage inflammatory protein-1α, MIP-1α), exerting suppressive effects on the tumor growth." (PMID 40136347, 2025). "Act-MG-1, based on expressing MHC-II, remarkably upregulated a series of transcription factors and cytokines (Ccl3, Ccl4, Jun, Junb, and Jund), indicating that this cluster of cells was a type of active microglia that can quickly respond to tumor stimulation." (PMID 39867913, 2024). "Specifically, CCL3 levels increased as tumor growth progressed and had a direct correlation with the presence of ulceration in the primary tumor." (PMID 38399429, 2024). "In contrast, we observed increased expression of Ccl3 in the anti-PD1 resistant tumor model compared to the parental model, indicating enhanced recruitment of immune cells and an adequate pro-inflammatory response in the resistant tumors." (PMID 39218928, 2024). "PGE2 is directly involved in the complex tumor inflammatory microenvironment, inhibiting inflammatory chemokines CCL3 and CCL4, preventing the accumulation of activated immune cells." (PMID 39450252, 2024). "Immunofluorescence staining experiments conducted on tumor‐bearing livers have substantiated the production of CCR5 ligands (CCL3/4/5) and cytokines (IL‐12/15/18) by KCs at the periphery of tumors." (PMID 39220104, 2024). "At the same time, extracellular tumor-promoting chemokines, such as CCL3, CCL5, CCL7, CCL11, CXCL1, and CXCL12, were also downregulated." (PMID 38779358, 2024). "Subsequent research revealed that PGRN knockout enhanced the host antitumor immunity, suppressed tumor growth, and upregulated chemokine CCL3 expression in the CD8+ T cells." (PMID 38744851, 2024). "Consistently, quantification of activated natural killer (NK) cells and CD8+ T cells in the metastatic liver showed that they were also preferentially enriched at the tumour margin, next to KCs expressing CCL3, CCL4, CCL5, IL-12, IL-15 and IL-18." (PMID 38326607, 2024). "Another study showed an increase in CD103+ DCs infiltration in CCL3-secreting CT26 tumor in comparison to WT CT26." (PMID 39179536, 2024).
tumor (continued). "The tumor-associated macrophages (TAM) exhibit reduced expression of the M1 genes Tnfa, Ccl3, and Il1b, but elevated levels of the M2 markers Ym1, Fizz1, Il1ra, Mgl1, and Mgl2 following the respective stimulation for M1 or M2 phenotype polarization." (PMID 38629061, 2024). "Second, this investigation overlooked the effect of PGRN on other tumor-infiltrating cell types, sch as macrophages regarding CCL3 secretion, which should be investigated in future studies." (PMID 38744851, 2024). "As verified by exocytotic chemokines, the expression of tumor-promoting chemokines, including CCL3, CCL5, CCL7, CCL11, CXCL1, and CXCL12, showed a downward trend after MWA." (PMID 38779358, 2024). "The NicheNet method showed that, with neutrophils as signal transmitters in the tumour‐invaded TDLNs, CCL3/CCL4–CCR1 pairs were also dominant in mediating the interactions between neutrophils and macrophages, consistent with the findings of CellChat analysis." (PMID 37491740, 2023). "From the immune response regulation aspect, 20 upregulated genes encoding chemokines with log2FC > 1.5 were selected, among which Ccl3, Ccl4, Cxcl9 and Cxcl16 shared with both tumor suppressive roles and effects in promotion of T cell infiltration 33–36." (PMID 37996458, 2023). "With CCL3 stimulation, the Ki67 was up-regulated in the tumor tissues and it was also reversed in the tumor tissues with VIRMA down-expression." (PMID 36691046, 2023). "The data showed that the CCL3 was mainly expressed in the cytoplasm of hepatocytes and intercellular matrix adjacent to the tumor tissue, with cancer cells and distant hepatocytes staining negative." (PMID 36691046, 2023). "Tumor-associated macrophages (TAM), a suppressive type of macrophage closely related to M2 macrophages, derive from tumor-associated monocytes that migrate to tumors via CCL2 and CCL3 gradients." (PMID 36167831, 2023). "Our study demonstrated that CCL3, which is secreted by hepatocytes, promotes tumor metastasis by fueling m6A modification in ICC." (PMID 36691046, 2023). "Together, these data demonstrated that CCL3 promotes the growth of ICC cells by regulating VIRMA/SIRT1 in ICC subcutaneous tumor mice model." (PMID 36691046, 2023). "Tumor growth of HuCCT1 ICC cells was significantly faster than that in the PBS group after CCL3 treatment, while HuCCT1 cells with VIRMA knockdown grew slower even after receiving CCL3 stimulation." (PMID 36691046, 2023). "β2AR signaling can also polarize macrophages from M1 to M2 type, thereby enhancing anti-inflammatory cytokines like IL-10, IL-4 & IL-13, and decreasing pro-inflammatory cytokines like INFγ, TNFα, IL1β, CCL2, CCL3 and CCL4 to cause tumor progression." (PMID 37006295, 2023). "Microglials_c1_CCL4 promoted the immune response by secreting chemokines such as CCL3/4 to recruit T cells, immature DCs, and NK cells in the tumor microenvironment." (PMID 36529697, 2023). "Beyond inhibitory cytokines, other strategies aim to stimulate key cytokines to reinvigorate anti-tumor immunity, such as using CCL3 cytokine synergistically with antigens (Nature)." (PMID 38259287, 2023). "The CC chemokines, CCL4 and CCL3, act alone or together by regulating the tumor immune microenvironment to promote tumor progression." (PMID 37745301, 2023). "The immunohistochemistry analyses confirmed that the expression of VIRMA, SIRT1, and Ki67 was upregulated in the tumor tissues with CCL3 stimulation, and it was also reversed in the tumor tissues with VIRMA down-expression." (PMID 36691046, 2023). "Our study demonstrated that cytokine CCL3, which is secreted by hepatocytes, promotes tumor metastasis by regulating m6A modification via vir-like m6A methyltransferase associated (VIRMA) in ICC cells." (PMID 36691046, 2023). "In particular, CCL2 and CCL3 have been found to have direct protumor effects by promoting tumor invasion and proliferation, survival, motility, and stemness and preventing apoptosis." (PMID 37373025, 2023).
tumor (continued). "CCL3 and CXCL1 are pro-inflammatory cytokines and recruit tumor-killing cells, while S100A8/A9 is linked to metastasis." (PMID 37553342, 2023). "Stimulated leukocytes, fibroblasts, and tumor cells produce CCL3 (MIP-1α) and CCL4 (MIP-1β), which induce chemotaxis of T cells, monocytes, NK cells, and dendritic cells by interacting with their specific receptor CCR5." (PMID 37465147, 2023). "We specifically showed that IL9-polarized TAMs induced antitumor immunity in mice by recruiting antitumor immune cells into the tumor mass via releasing the macrophage-derived chemoattractants, CCL3/4 and CXCL9/10." (PMID 36968220, 2023). "By causing monocytes to secrete the matrix metalloproteinase 9 (MMP9) enzyme, CCL2 and CCL3 can promote the extravasation of tumor cells." (PMID 37373025, 2023). "CCL3 can stimulate cancer cell growth and migration, whereas blocking CCL3 can suppress tumor growth, and angiogenesis, and increase cell sensitivity to therapeutic drugs." (PMID 38274108, 2023). "Tumor-infiltrating basophils produce CCL3 and CCL4 to promote the recruitment of CD8+ T cells into the tumor microenvironment enhancing tumor rejection." (PMID 35693800, 2022). "The tumor proliferative ability of CCL3 was weakened after RNA interference; while the proliferative ability of HCT116 cells was enhanced after overexpression of CCL3." (PMID 35935327, 2022). "M-MDSCs are recruited to tumors via a CCL1, CCL5-induced chemokine cascade that is disseminated by tumor cells, and CCL3 produced by TAMs is retained in the primary tumor." (PMID 36686745, 2022). "Accordingly, they significantly increased the ratios of cDCs and T cells in CD45+ cells in the MC38 tumor, except CCL3." (PMID 36654820, 2022). "N1 TANs have efficient tumor cell killing capability and high expression of immune activation related cytokines and chemokines, including CCL3, CXCL9, and CXCL10, which promote the recruitment and activation of CD8+ T cells." (PMID 36514901, 2022). "High IL-37 expression by HCC tumor cells is associated with upregulated levels of CCL3 and CCL20 and increased recruitment of CD1a+ dendritic cells (DCs) in tumor infiltrations." (PMID 36551790, 2022). "Injection of the CCR5 inhibitor maraviroc into mice-inhibited tumor proliferation and reduced the expression of CCL3, CCL4, and CCL5." (PMID 35935327, 2022). "We show that tumor derived factors prime hematopoietic stem and precursors cells (HSPCs) to secrete CCL3 and 4 that promote HSPC differentiation into protumoral MDSCs via CCR1 and CCR5 signaling." (PMID 35064009, 2022). "Fluorescence-activated cell sorting (FACS) analysis showed that CCL19, CCL21, and XCL1 boosted the ratios of DCs and T cells in CD45+ leukocytes while CCL3 increased the percentage of CD45+ leukocytes in total cells in MC38 tumor." (PMID 36654820, 2022). "A preclinical study in a colorectal mouse model reported that the secretions of CCL-3 from CT26 tumor cells change the inflammatory response in the early phase of tumor response." (PMID 36686835, 2022). "Transcriptome functional and cytokine analysis indicated that tumor derived factors induced CCL3 and CCL4 in HSPCs that, through the autocrine engagement of CCR1 and CCR5, induced HSPCs differentiation in MDSCs." (PMID 35064009, 2022). "The transcriptome analysis also revealed that tumor derived factors induced bone marrow cells to transcribe CCL3, CCL4, and other ligands of CCR1 and CCR5." (PMID 35064009, 2022). "DEGs upregulated in subtype 1 included chemokine CCL3, which is frequently overexpressed in tumor sites, leading to microenvironmental dysfunction." (PMID 35631431, 2022). "Further studies demonstrated that HSPCs primed by tumor derived factors produce CCL3-4, which act via autocrine or paracrine mechanisms on CCR5 and CCR1 to promote the differentiation of tumor associated neutrophils with immunosuppressive properties." (PMID 36561751, 2022).
tumor (continued). "In the role of anti-tumor immunity, mast cells secreted CCL3 and CXCL10 to recruit NK cells, CD4+ helper T cells, and CD8+ cytotoxic T cells." (PMID 35563678, 2022). "As one of the receptors of CCL3, CCR5 was regarded to be able to interact with inflammatory factors and tumor-associated genes to regulate NF-κB pathway participating in the development of cancer." (PMID 33981848, 2021). "MIP-1α/CCL3 has inhibited the progression of established tumors by the preferential recruitment of anti-tumor immune cells and the production of anti-tumor chemokines." (PMID 34885960, 2021). "In mouse melanoma models, tumor-infiltrating basophils seemed to increase infiltration of CD8+ T cells by producing chemokines CCL3 and CCL4, leading to tumor rejection after depletion of Treg cells." (PMID 34209038, 2021). "Expression array analysis revealed that both baseline and tumor cell-induced expression of the chemokines CCL3, CCL4, and CCL5 were markedly reduced in MEKK1−/− mammary fibroblasts." (PMID 33868996, 2021). "Circulatory and tumor associated levels of CCR5 and its cognate ligands (CCL3, CCL4, CCL5) were analyzed by ELISA, qRT-PCR and immunohistochemistry." (PMID 32902795, 2021). "In the tumor-draining lymph nodes, antitumor immunity is driven by CCL3-dependent interferon gamma (IFNγ) production and CCL3-induced dendritic cells maturation." (PMID 36046113, 2021). "Our co-culture experiment showed that FLI1 is involved in CCL3 secretion of TAMs and promotes tumor cell invasion." (PMID 33971970, 2021). "It has been proposed that expression of CCL3, 4, and 5 in the tumor mass drives the recruitment of ARG1+CCR5+ LDNs18 in tumors." (PMID 34301813, 2021). "This anti-tumor effect was mediated by recruitment of CD8 T cells and NK cells likely by CCL3 secretion, IL-6 secretion potentially leading to an anti-proliferative impact on tumor cells, and also reduced mature blood vessel density." (PMID 34063789, 2021). "In mice, circulating cDC precursors (pre-cDCs) expressing the chemokine receptors CCR1 and CCR5 migrate into the tumor site through attraction to CCL3, which is produced by tumor cells." (PMID 34572844, 2021). "Contrary to the serum profile, urine from OH-BBN induced C57BL/6 mice displayed increased levels of the pro-inflammatory cytokines Ccl3 and Il1β, as well as an upregulation of tumor promoting Ppp1r2, Pak4, tumor growth marker Nadk, and Dctn2." (PMID 34232958, 2021). "In MM, the mechanism explaining the increased number of tumour-associated macrophages (TAM) in unclear; however, the roles of CCL2 and CCL3 in the process have been confirmed." (PMID 33808304, 2021). "In vitro experiments found that upregulated CCL3 inhibits the immune response which would favor tumor growth." (PMID 34893045, 2021). "Activated mast cells recruit tumor-associated macrophages by CSF2, CCL3, and IL-6 secretion, resulting in increased tumor growth, as shown in a gastric cancer murine model." (PMID 34063789, 2021). "In the large majority of tumor types, Il12b, Ifng, Ccl4, Ccl5, Cxcl9, and Cxcl10 showed a significant positive correlation with infiltration of M1 macrophages, with Ccl3 displaying a lesser overall correlation." (PMID 34446712, 2021). "It has been shown that chemokines (such as chemokine C-C motif ligand 3, CCL3), produced by BC cells attract MDSCs to the primary tumor site, which in turn activate EMT in BC cells enhancing breast tumor invasion." (PMID 34638283, 2021). "In this study, we analyzed the circulatory and tumor-associated levels of CCR5 and/or its ligands (CCL3, CCl4, CCL5) via ELISA and qRT-PCR/IHC, respectively." (PMID 32902795, 2021). "NK cells are another lymphoid cell subtype that can be recruited to the tumor microenvironment through mast-cell-secreted chemokines such as CCL3 and CXCL8 and are activated in a contact-dependent manner by mast cells to secrete IFN-γ." (PMID 34063789, 2021).
tumor (continued). "In comparison with adjacent and precancerous tissues, we found a significant reduction of CD40+, CD27+, KLRB1+, and CCL5+ B cells (clusters 4, 9, 1, and 3, respectively) and MZB1+, DUSP1+, and CCL3+ plasma cells (clusters 5, 7, and 8) in tumor tissues." (PMID 34185431, 2021). "Overexpressing chemokines, such as CCL2 (MCP-1) and CCL3, accompanying the recruitment of macrophages, is a common phenomenon in human tumours." (PMID 33808304, 2021). "That is the case of Nr4a1, Ccl2, and Ccl3, which antagonize tumor growth by attracting tumor-suppressive immune cells." (PMID 33330473, 2020). "Tumor-infiltrating M-MDSCs produce CCR5 ligands CCL3, CCL4, and CCL5, and meanwhile, Tregs exhibit high surface expression of CCR5 and are recruited to tumor tissue by CCL4 and CCL5." (PMID 32793192, 2020). "The N1 phenotype is involved in cytotoxic activity against tumor cells and its immune profile is characterized by high levels of TNFα, CCL3, ICAM-1 and low levels of Arginase." (PMID 32731512, 2020). "In Ret transgenic mouse models (melanoma model), tumor M-MDSCs also drove the recruitment of CCR5+ Treg cells through producing chemokines such as CCL3, CCL4 and CCL5, further accelerating tumor metastasis." (PMID 33613512, 2020). "Among the upregulated genes in the TAM-like macrophages, we focused on CC chemokine ligand 3 (CCL3), which was reported to contribute to tumor progression in several malignancies." (PMID 32457351, 2020). "In a tumor, an active immune response results in the production of CCL3 and CCL4 by B cells and basophils." (PMID 33076281, 2020). "The decrease in the levels of Fosl1, Ccl2, and Ccl3 is expected to reduce the recruitment of cells that allow tumor cells to evade the immune surveillance, e.g., TAMs, regulatory T cells (Tregs), and myeloid-derived suppressor cells (MDSCs)." (PMID 33330473, 2020). "Although CCL3 and CCL4 have an anti-cancer effect by causing cytotoxic TIL infiltration to the tumor, they can support the development of the tumor if they act directly on a cancer cell." (PMID 33076281, 2020). "The majority of tumor-associated macrophages (TAMs) expressed proinflammatory cytokine/chemokine genes, such as IL1B, CCL2, CCL3, and CCL20." (PMID 33277616, 2020). "In different transplantable tumor models, this process was shown to be largely driven by the tumor expression of CCL3, a ligand of CCR1 and CCR5, two chemokine receptors expressed by pre-cDCs." (PMID 32486257, 2020). "Activation of CCR2 signaling prompts TAMs to secrete another chemokine, CCL3, leading to enhanced TAMs–tumor cell interaction and prolonged retention of TAMs in the metastases sites, which promotes extravasation of breast cancer cells." (PMID 33414786, 2020). "CCL3 contributes to tumor progression and poor prognosis in ESCC patients by binding CCR5 on ESCC cells, activating PI3K/Akt and MEK/ERK pathways, upregulating MMP-2 and VEGF-A expression, and promoting cell migration, invasion, and angiogenesis." (PMID 32457351, 2020). "To confirm that CCL3 and CCL4 secretion are sufficient to induce chemoattraction in distant CTLs, we engineered tumour cells that constitutively secrete both chemokines, or CCL3 or CCL4 alone." (PMID 33046212, 2020). "Our examination of double IF showed that CCL3 was expressed in both neoplastic cells and TAMs in the tumor nest of human ESCC tissue." (PMID 32457351, 2020). "The expression of chemokines for CCR2 (Ccl2 and Ccl7) or CCR5 (Ccl3, Ccl4, and Ccl5) in tumor-bearing lungs, chemoattractants for monocytes/macrophages, was unchanged in FROUNT-cKO mice." (PMID 32001710, 2020). "In this report, we have shown that CCL3/4/5–CCR5 axis facilitates tumor progression by the interaction between MSCs and CRC cells." (PMID 30890699, 2019).